SIRT2 (sirtuin 2)
Diseases named in the same sentence as SIRT2 in open-access papers (continued):
Sharing a sentence is not in itself a finding about the gene and the disease.
Obesity (continued). "In mice, Sirt2 deletion aggravates HFD-induced obesity, promotes glucose intolerance and insulin resistance, exacerbates hepatic steatosis, and increases lipid deposition via the ER stress pathway." (PMID 39372420, 2024). "It has been previously published that SIRT2 protected against metabolic disorders, oxidative stress, mitochondrial dysfunction, insulin resistance, inflammation, obesity, and cardiomyocyte senescence." (PMID 37240315, 2023). "Consistent with the results of this study, others have shown that diabetes and obesity reduce the expression of Sirt1, Sirt2, Sirt3, and Sirt6." (PMID 38134189, 2023). "HIF-1α represses SIRT2 expression and promotes obesity, while SIRT2 knock-out animals develop obesity, hepatic steatosis, and ER stress." (PMID 36834782, 2023). "We and others have shown that SIRT2 deacetylates and deactivates NFκB p65 and prolongs the immunosuppressive hypo-inflammatory phase of sepsis with obesity, a common co-morbidity in sepsis patients." (PMID 36865524, 2022). "The oxidative stress of obesity with sepsis directly oxidizes SIRT2 to deactivate its deacetylation-function and exaggerates hyper-inflammation." (PMID 35052507, 2021). "Our earlier studies implicate an obesity-specific role of SIRT2 in innate immune cells during sepsis." (PMID 35052507, 2021). "In obesity, adipose SIRT2 expression is suppressed by adipose hypoxia-induced cellular hypoxia-inducible factor 1-α (HIF1α), which prevents SIRT2-mediated post-translational deacetylation and activation of PGC-1α and its FAO transcriptional gene program." (PMID 33193730, 2020). "SIRT2, far less studied than SIRT1, is emerging as distinctly important in obesity and inflammation, including obesity associated with sepsis." (PMID 30216989, 2018). "Specifically, we showed that SIRT2 expression decreases during hyper-inflammation and increases during the hypo-inflammatory phase in obesity with sepsis via direct deacetylation of NFĸB p65." (PMID 30216989, 2018). "We have recently shown that the relationship between obesity with sepsis and SIRT2 is a two-way street." (PMID 30216989, 2018). "Adipocyte-specific HIF1α inactivation leads to increased expression of SIRT2 and attenuates dietary-driven obesity in mice." (PMID 30574122, 2018). "The striking dichotomy between SIRT1 and SIRT2 in nuclear functions and physiologic effects in lean vs. hyper nutrition with obesity is not fully understood." (PMID 30216989, 2018). "We implicate SIRT-2 as a novel checkpoint for guarding homeostasis in obesity, but with persistent activity adversely affect survival." (PMID 27500833, 2016). "Secondly, the exact mechanism of how obesity modulates SIRT-2, especially during the acute inflammatory states, needs to be further elucidated." (PMID 27500833, 2016). "E-selectin and ICAM-1 expression increased in AK-7 vs. vehicle treated mice, supporting a role for SIRT-2 in repressing inflammatory reactions in microvasculature during obesity with sepsis." (PMID 27500833, 2016). "Previous reports suggest that HIF-1α may indirectly influence PGC-1α activity by suppressing sirtuin 2 (SIRT2)-mediated deacetylation in dietary obesity mouse models." (PMID 40713487, 2025). "This indicated that Sirt2 knockout promoted primary obesity in mice." (PMID 39004743, 2024). "In summary, here we found that Sirt2 deletion leads to impaired glucose tolerance and insulin resistance, induced primary obesity; Sirt2 severely disrupts liver function in mice under metabolic stress, exacerbating the metabolic burden on the liver and impacting glucose metabolism." (PMID 39004743, 2024). "The present study, which is related to one of the newly discovered alga-based adiponectin-modulating formulas, NBF2, showed that its intake caused Sirt2 and dual PPAR activation, up-regulated APN, and improved glucose and lipid metabolism in a rodent model of obesity and T2DM." (PMID 39409158, 2024).
Obesity (continued). "Similarly, in obesity with sepsis, Sirt2 expression and activity decrease during hyper-inflammation, while during hypo-inflammation, total Sirt2 expression increases, and SIRT2 deactivates NF-κB to mediate immune repression in mice." (PMID 39372420, 2024). "Our findings reveal a role for SIRT2 in the regulation of hepatic lipid homeostasis, potentially through the ER stress response, suggesting that SIRT2 activation might constitute a therapeutic strategy against obesity and its metabolic complications." (PMID 35743232, 2022). "SIRT2 activation might constitute a therapeutic strategy against obesity and its metabolic complications." (PMID 35743232, 2022). "Furthermore, SIRT2 showed prevention of obesity and metabolic diseases, which were important factors involved in CAD pathogenesis." (PMID 35224092, 2022). "Moreover, SIRT2 expression was negatively correlated with OS, obesity and insulin resistance in human PBMCs." (PMID 34685718, 2021). "It was further hypothesized that the insulin resistance due to diet-induce obesity would be exacerbated with deletion of the SIRT2 gene." (PMID 30533032, 2018). "SIRT-2 regulates microvascular inflammation in obese mice with sepsis and may provide a novel treatment target for obesity with sepsis." (PMID 27500833, 2016). "The link between SIRT2 and fatty acid oxidation appears to be elusive, and the development of diet-induced obesity in mice may be attributed to SIRT2 repression and attendant reduced β-oxidation." (PMID 27916001, 2016). "SIRT-2 is the most abundant of sirtuins in the white adipose tissue where it critically regulates adipocyte growth in obesity; SIRT2 expression is down- regulated in differentiating pre-adipocytes to increase glycolysis and decrease fatty acid oxidation, allowing adipogenesis to occur." (PMID 27500833, 2016). "SIRT2, the cytoplasmic member of the sirtuin family, is generally acknowledged to promote cancer and contribute to the progression of various pathologies, including neurodegeneration, inflammation, obesity, and bacterial infection through the deacetylation of target substrates." (PMID 41805109, 2026). "Furthermore, we found that deletion of Sirt2 led to impaired glucose tolerance and insulin resistance, and induced primary obesity; Sirt2 severely disrupted liver function in mice under metabolic stress, exacerbating the metabolic burden on the liver and affecting glucose metabolism." (PMID 39004743, 2024). "Conversely, dietary obesity and associated pathologies, e.g. IR, is linked to the capacity to suppress β-oxidation in visceral adipocytes, in part through transcriptional repression of SIRT2 with negative effects on the SIRT2-PGC1α regulatory axis." (PMID 33639916, 2021). "Therefore, hypoxia-induced reductions of SIRT2 in obesity may contribute to adipocyte dysregulation by limiting oxidative capacity and increasing lipid mass." (PMID 33193730, 2020). "In addition, SIRT2 may act as a nutrient sensor regulating primary cilia formation, suggesting possible application as a treatment for obesity." (PMID 32213867, 2020). "From the SIRT perspective this seems likely, but whether SIRT-2 is specific for obesity is unknown." (PMID 27500833, 2016). "This inhibitory effect of SIRT2 on adipocyte differentiation discloses under nutritional stress suggesting that combination of SIRT2 activators with diet could provide novel therapeutic strategy for obesity." (PMID 27104517, 2016). "Whether SIRT-2 participates in obesity related acute inflammation is largely unknown." (PMID 27500833, 2016). "Rhein’s binding to SIRT2 inhibits NLRP3 inflammasome activation in macrophages, promoting white adipose tissue thermogenesis during obesity." (PMID 41567643, 2025). "Overall, these findings suggest that high expression of SIRT1 and SIRT3 and low expression of SIRT2 and SIRT6 produced a metabolic state that inhibited the development of obesity, thereby reducing the occurrence of obesity." (PMID 36581622, 2022).
Obesity (continued). "Of note, SIRT1 and SIRT2 exert a dual effect on the progression of DM, while SIRT6 overexpression exacerbates diet-induced obesity." (PMID 36581622, 2022). "By contrast, SIRT2 protein expression in visceral WAT from human obese subjects and a mouse model of diet-induced obesity is downregulated compared with that in WAT from lean controls." (PMID 30574122, 2018). "HIF-1α hinders adipocyte-mediated fatty acid catabolism by blocking SIRT2-PGC-1α pathway, thereby favoring the progression of obesity." (PMID 30559718, 2018). "Unlike FASN and leptin, sirtuin 2 (Sirt2) and the peroxisome proliferator-activated receptors alpha and gamma (PPAR-α/γ) are known to improve obesity-associated metabolic disorders and are considered therapeutic targets for diseases such as T2DM." (PMID 39409158, 2024). "In contrast, SIRT2 and SIRT6 promote the occurrence and development of obesity." (PMID 36581622, 2022). "Therefore, it can be expected that in the future activation of SIRT1 and SIRT2 or inhibition of SIRT7 by appropriate miRNA, may be a therapeutic strategy for the treatment of obesity." (PMID 27104517, 2016). "In our previous work, we showed that nutritional overload in obesity may enhance the expandability of VAT, specifically over SAT, which may occur via downregulation of expression of the histone deacetylases sirtuin 1 (SIRT1) and sirtuin 2 (SIRT2) in the resident adipose staminal cells (ASCs)." (PMID 35806353, 2022). "As an example, lack of SIRT1-, SIRT2-, and SIRT6-dependent deacetylation and activation of specific adipose gene programs was shown to contribute to the development of metabolic disorders, such as type 2 diabetes and obesity." (PMID 34829720, 2021). "Altogether, the lack of SIRT1-, SIRT2- and SIRT6-dependent deacetylation and activation of specific adipose gene programs can contribute to the development of metabolic conditions, including obesity and T2D." (PMID 33193730, 2020).
cardiac hypertrophy (37 papers, 2018 to 2026). "CA4 and HIF‐1α are associated with cardiac hypertrophy, whereas SIRT2 is negatively associated with hypertrophic cardiac disease." (PMID 40898929, 2026). "It has been shown previously that SIRT2 deficiency exaggerates aging-related cardiac hypertrophy via AMPK inhibition by binding to LKB1, a major upstream kinase of AMPK." (PMID 40197001, 2025). "SIRT2 levels are decreased in mice during pathological cardiac hypertrophy and SIRT2 deficient mice develop pathological cardiac hypertrophy and cardiac dysfun-ction." (PMID 33806509, 2021). "The previous study implicated the histone deacetylase SIRT2 in the activation of AMPK via LKB1 to repress cardiac hypertrophy." (PMID 32625104, 2020). "In the present study, we found similar results as SIRT2 deficiency induces spontaneous cardiac hypertrophy in mice." (PMID 29504933, 2018). "In our recent work, we also found that SIRT2 deficiency induces spontaneous cardiac hypertrophy in mice through hyperactivation of NFAT transcription factors." (PMID 29504933, 2018). "In our recent work, we also found that SIRT2 deficiency induces spontaneous cardiac hypertrophy in mice by hyperactivation of NFAT transcription factors." (PMID 29504933, 2018). "SIRT2-deficient mice exhibit increased global protein synthesis in the hearts, which may contribute to the development of cardiac hypertrophy." (PMID 41813942, 2026). "Considering the close relationship between SIRT2 and metabolic homeostasis, as well as the protective role of SIRT2 in pathological cardiac hypertrophy, we explored the effect of SIRT2 on DCM and lipid metabolism." (PMID 39781464, 2025). "SIRT2 activates AMPK by deacetylating the kinase LKB1, and the loss of SIRT2 diminishes AMPK activation and contributes to aging‐related cardiac hypertrophy." (PMID 41180381, 2025). "A previous study revealed that Sirt2 knockout significantly exaggerated cardiac hypertrophy and fibrosis in elderly mice." (PMID 40197001, 2025). "Conversely, SIRT2 overexpression can effectively ameliorate aging-related cardiac hypertrophy by activating the liver kinase B1 (LKB1)-AMPK pathway." (PMID 40197001, 2025). "EPC-derived exosomal (circ_0018553) reduced Ang II-induced cardiac hypertrophy by effectively regulating the miR4731/Sirt2 signaling pathway." (PMID 41567643, 2025). "SIRT2 knockout significantly worsened cardiac hypertrophy and fibrosis while reducing ejection fraction and fractional shortening in 24‐month‐old mice." (PMID 41180381, 2025). "Loss of SIRT2 reduces AMPK activation, promotes age-associated and angiotensin II (Ang II) -induced cardiac hypertrophy, and attenuates metformin-mediated cardioprotective effects." (PMID 39226168, 2024). "In Ang II -induced cardiomyocyte hypertrophy, PHD protein 19 (PHF19) fosters cardiac hypertrophy by epigenetic inhibition of SIRT2 expression." (PMID 39226168, 2024). "In the heart, SIRT2 potentially modulates cardiac fibrosis by affecting cardiac hypertrophy and myocarditis." (PMID 39226168, 2024). "SIRT2 can bind to the Nuclear Factor of Activated T Cells 2(NFATc2) and deacetylate it, further repressing the occurrence of pathological cardiac hypertrophy." (PMID 39226168, 2024). "Comparatively, SIRT2-knockout mice, in contrast to their wild-type counterparts, displayed exacerbated cardiac hypertrophy, fibrosis, and compromised cardiac function following angiotensin II infusion." (PMID 39871888, 2024). "Functionally, circ_0018553 sponged miR-4731 which targets sirtuin 2 (SIRT2) expression, a deacetylase that protects against cardiac hypertrophy." (PMID 38259314, 2023). "Genetic deletion of SIRT2 resulted in an accelerated aging phenotype, such as spontaneous cardiac hypertrophy, fibrosis, and overall dysfunction, whereas overexpression of SIRT2 improved viability in cultured myocytes." (PMID 35958271, 2022). "Here in this work, we observed that PHF19 promoted cardiac hypertrophy via epigenetically targeting SIRT2." (PMID 33611744, 2021).
cardiac hypertrophy (continued). "During cardiac hypertrophy, Ang II treatment reduced the enrichment of H3K36me3 at Sirt2 promoter in heart tissues, which was blocked by Phf19 knockdown." (PMID 33611744, 2021). "The loss of SIRT2 inhibits the activation of AMPK, promotes ageing‐related and/or angiotensin II (Ang II)‐induced pathological cardiac hypertrophy and weakens the metformin‐mediated cardiac protection." (PMID 34028177, 2021). "In the present study, we identified that PHF19 promoted cardiac hypertrophy via downregulating SIRT2." (PMID 33611744, 2021). "In the present study, we provided evidence that PHF19 promotes cardiac hypertrophy via epigenetically repression SIRT2 expression." (PMID 33611744, 2021). "In mice with cardiac-specific SIRT2 overexpression, Ang II-induced cardiac hypertrophy was repressed and cardiac dysfunction was rescued, whereas cardiac-specific depletion of Sirt2 dramatically aggravated hypertrophic response to Ang II stimulation." (PMID 35118147, 2021). "In particular, SIRT2 restrains cardiac hypertrophy by deacetylating LKB1 and activating LKB1-AMPK signaling." (PMID 34379189, 2021). "SIRT2 was reported to repress cardiac hypertrophy via diverse mechanisms, including activation of AMPK and repression of GSK3b and NFATc2." (PMID 33611744, 2021). "SIRT2 knockout markedly exaggerates cardiac hypertrophy and fibrosis as well as decreases in cardiac ejection fraction and fractional shortening in aged mice." (PMID 32765957, 2020). "Conversely, cardiac-specific SIRT2 overexpression is able to protect the hearts against Ang II-induced cardiac hypertrophy and fibrosis and rescued cardiac function." (PMID 32765957, 2020). "A previous study showed that the acetylation of GSK3β increases in pathological cardiac hypertrophy and that SIRT2 binds to, deacetylates and activates GSK3β." (PMID 31105527, 2019). "In our recent work, we demonstrated the development of spontaneous cardiac hypertrophy in SIRT2-KO mice." (PMID 29504933, 2018). "PHF19 epigenetically regulated SIRT2, which aided in the development of heart hypertrophy." (PMID 41567643, 2025). "Sirt2 protects mice against both aging-related and Ang II-induced cardiac hypertrophy through activating AMPK by deacetylating LKB1, indicating that Sirt2 may be a potential target for the treatment of cardiac hypertrophy." (PMID 40523615, 2025). "In addition to regulating AMPK pathway, Sirt2 can also deacetylate NFATc2 and inhibit the pathological of myocardial hypertrophy." (PMID 40523615, 2025). "MiR-4731 overexpression promoted cardiac hypertrophy by targeting sirtuin 2 (SIRT2)." (PMID 39850481, 2024). "Inhibits miR-4731, which targets SIRT2, reducing Ang II-induced cardiac hypertrophy." (PMID 38669371, 2024). "Additionally, our studies provide a novel approach for treatment of cardiac hypertrophy and injury by targeting SIRT2 pharmacologically, providing a novel avenue for the treatment of these disorders." (PMID 37728319, 2023). "Finally and most importantly, we show that pharmacological inhibition of SIRT2 protects the heart against the development of cardiac hypertrophy, opening potential treatment for this disorder." (PMID 37728319, 2023). "Additionally, Sirt2-/- mice displayed evidence of less cardiac hypertrophy, as evidenced by lower interventricular septal (IVS) thickness on echocardiography, and reduced cardiac size and heart weight to body weight ratio on gross examination." (PMID 37728319, 2023). "Finally, treatment of mouse hearts with a specific SIRT2 inhibitor reduced cardiac size and attenuates cardiac hypertrophy in response to PO." (PMID 37728319, 2023). "Finally, we provide a clinical significance for our findings and show that treatment of mice with AGK2, a selective SIRT2 inhibitor, results in protection against cardiac hypertrophy in response to PO." (PMID 37728319, 2023).